ITGAV (integrin subunit alpha V)
Diseases named in the same sentence as ITGAV in open-access papers (continued):
Sharing a sentence is not in itself a finding about the gene and the disease.
tumor (169 papers, 2006 to 2026). "Through Cox regression and Kaplan‒Meier analyses, we found that ITGAV expression is closely linked to tumor progression and poor prognosis in various malignant solid tumors." (PMID 40775249, 2025). "Integrin αV (ITGAV) plays a key role in cell adhesion, migration, and immune regulation, and is implicated in tumor progression." (PMID 40775249, 2025). "In recent years, aberrant expression of ITGAV has been clearly identified in various tumor studies, suggesting that ITGAV is closely associated with tumor development and metastasis." (PMID 40018050, 2025). "Our study reveals the potential of ITGAV as a diagnostic and prognostic biomarker, while also demonstrating its key regulatory role in immunotherapy and tumor metastasis, providing a promising novel target for digestive system cancers treatment options." (PMID 40018050, 2025). "The activation of IGF1Rβ associated with the HSPA1L/ITGAV complex enhances the tumor stemness and radiotherapy resistance of non-small cell lung cancer through downstream AKT/NF-κB or AKT/GSK3β/β-catenin activation pathways." (PMID 39239559, 2024). "ITGAV was upregulated in human ESCC tumour tissues and increased ITGAV protein levels were associated with poor prognosis." (PMID 34709754, 2021). "Here it is remarkable that ITGAV is primarily detectable in advanced tumors, which underlines the potential role of integrin expression during tumor progression." (PMID 33110104, 2020). "Next, we analyzed mutations in the ITGAV gene in all tumor tissues through the cBioPortal platform." (PMID 40018050, 2025). "In addition to FN1, high risk of tumor recurrence was associated with higher expression of ITGAV, ITGB1 and ITGB6." (PMID 40423510, 2025). "Additionally, our meta-analysis revealed that NTRK2 is strongly associated with ITGAV, the other key player in tumor metastasis." (PMID 40133476, 2025). "Likewise, ITGAV expression allows early identification of those cSCC patients who are at risk of tumor relapse, reinforcing the need for prognostic biomarkers in cSCC patients’ management." (PMID 39075581, 2024). "Additionally, we found an association of NOPE with ITGAV expression (detectable in 14.3% of all tumors) on tumor cells (P = 0.021)." (PMID 35246597, 2022). "Moreover, ITGAV expression was positively associated with scores for all immune stromal cells, immune cells, and estimated scores (tumor purity), suggesting its close associations with TME." (PMID 35927660, 2022). "To gain insight into how the ITGAV knockdown might cause the reduction in tumor growth and metastasis/carcinomatosis formation observed in vivo, we performed whole human genome expression analyses." (PMID 34174926, 2021). "The results indicated that prioritized proteins, CSTB, NDRG1, PGK1, and ITGAV, may play a relevant biological role in tumor progression, since they were potentially associated, directly or indirectly, with patient prognosis." (PMID 30185791, 2018). "A comparable enhancement in phagocytosis was observed with primary murine peritoneal macrophages (p < 0.05), validating the role of ITGAV in tumor immune evasion mechanisms." (PMID 41168993, 2026). "Forced ITGAV expression partially reversed the suppressive effects of miR-10b-3p on tumor cell proliferation, migration, invasion, and EMT." (PMID 42263107, 2026). "In cancer, dysregulated integrin signaling, often driven by aberrant expression or activation of specific integrin subunits such as ITGAV, contributes to tumor progression, metastasis, and treatment resistance." (PMID 40739706, 2025). "Mechanistically, POSTN interacts with integrin ITGAV/ITGB5 on tumor cells, activating the PI3K/AKT/β-catenin pathway and promoting epithelial-mesenchymal transition (EMT) phenotype." (PMID 40520021, 2025). "A unique cluster of tumor cells in D‐TGCT is identified that regulated differentiation of CD34+ fibroblasts into MMP3+ fibroblasts or APOE+ fibroblasts via COL6A3 − (ITGAV + ITGB8) interaction." (PMID 40126353, 2025).
tumor (continued). "We analyzed the correlation of FN1, ITGA4, ITGA5, ITGAV, ITGB1, ITGB3 and ITGB6 with disease status, risk of tumor recurrence according to the 2015 American Thyroid Association guidelines, and patient outcome." (PMID 40423510, 2025). "Upon comparing normal and tumor tissues, ITGAV expression was markedly increased in the colon, pancreas, liver, and esophagus." (PMID 40018050, 2025). "ITGAV expression is correlated with tumor immune cells, indicating its potential as an immunotherapeutic target." (PMID 40775249, 2025). "further elucidating that NET-DNA activation of ITGAV/NFκB signaling increased tumor proliferation, activation, metastasis, and adversely influenced prognosis." (PMID 40761249, 2025). "The depletion of ITGAV from dHL-60 cells reduces the cell killing of tumor cells by dHL-60 cells, suggesting ITGAV is involved in mediating the interaction between the two cells." (PMID 39941753, 2025). "Several genes, including S100A4, ITGAV, and COL3A1, previously linked to tumor progression and poor prognosis, emerged in our study as robust prognostic indicators." (PMID 40943183, 2025). "For example, ITGAV was an immunomodulatory protein that promoted T-cell activation during priming to enhance anticancer efficacy in tumor models." (PMID 40018050, 2025). "Myofibroblasts showed high overlap with regions of high COL4A1 expression, and both myofibroblasts and tumor cells showed overlap with the areas of high ITGAV expression." (PMID 39639369, 2024). "Here, we demonstrate that integrin αV (ITGAV) is a prognostic biomarker of tumor relapse, detecting cSCC epithelial plastic cancer cells with a hybrid E/M phenotype and an increased ability to progress to the aggressive mesenchymal phenotype." (PMID 39075581, 2024). "Taken together, these data indicate that THBS1 is a crucial matrix molecule that mediates tumor cell migration through interaction with adhesion receptor ITGAV." (PMID 39304722, 2024). "For the immunologic significance, NPC2 and ITGAV were positively correlated with the abundance of tumor‐infiltrating lymphocytes and macrophages." (PMID 39690926, 2024). "Here, we show that ITGAV expression in primary cSCC patient samples is predictive of tumor relapse, although it would be interesting to analyze this marker in an independent cohort." (PMID 39075581, 2024). "Given the aggressive growth and enhanced metastasis associated with patient cSCC relapses and the scarcity of prognostic biomarkers, we tested the plasticity marker ITGAV as a prognostic biomarker of tumor relapse in cSCC patient samples." (PMID 39075581, 2024). "The role of the ITGAV gene in tumour progression has been extensively studied, particularly regarding its involvement in the invasion and metastasis of HCC." (PMID 39428564, 2024). "Cell sratches analysis showed that overexpression of ITGAV significantly promoted the migration of tumor cells at 24 and 48 h after transfection, while knockdown of ITGAV remarkably inhibited the migration of tumor cells." (PMID 38374893, 2024). "The result of transwell assay also showed that overexpression of ITGAV promoted the migration and invasion of tumor cells." (PMID 38374893, 2024). "From the CCK-8 experiment, we found that overexpression of ITGAV obviously promoted tumor cell proliferation at 48 and 72 h after transfection, while knockdown of ITGAV markedly inhibited the proliferation of tumor cells." (PMID 38374893, 2024). "To further characterize the presence of COL4A1 and ITGAV in ccRCC, we examined the Clinical Proteomic Tumor Analysis Consortium (CPTAC), The Cancer Genome Atlas (TCGA), and the Genotype-Tissue Expression (GTEx) project." (PMID 39639369, 2024). "Overall, these results indicated that integrin containing the ITGAV subunit in dHL-60 cells is responsible for the cell–cell interaction and neutrophil-induced tumor cell-killing." (PMID 38806658, 2024).
tumor (continued). "The result indicated that the expression levels of NPC2 and ITGAV are related to GICs prognosis and tumor—immune signature." (PMID 39690926, 2024). "We compared the expression of Ecad, Vim, and ITGAV in cancer cells of primary tumors (Rel-PT) and in their respective local tumor relapses (Rel-R) using IF assays." (PMID 39075581, 2024). "We also detected that ITGAV knockdown inhibited the proliferation of tumor cells stimulated by NET-DNA." (PMID 38326837, 2024). "Taken together, these data illustrated that NET-DNA promoted the proliferation and metastasis of tumor cells via interaction with ITGAV." (PMID 38326837, 2024). "In the cell apoptosis analysis, overexpression of ITGAV significantly inhibited tumor cell apoptosis." (PMID 38374893, 2024). "The results showed that the expression patterns of SPP1 and CSF1 in normal and tumor tissues were most similar to those of ITGAV and PLAUR, respectively." (PMID 37097499, 2023). "Protein–protein interaction analysis revealed a strong association of ANGPTL proteins with several tumor-suppressor proteins such as ITGB3, ITGAV, and RASSF5." (PMID 37375208, 2023). "Integrin subunit αv (ITGAV) has been identified as an EMT marker in breast cancer and is associated with tumour cell detachment leading to metastatic spread of the tumour." (PMID 37174052, 2023). "ITGAV is located on chromosome 2q31‐q32, and as a protein‐coding gene, it is closely related to tumor angiogenesis, invasion and metastasis." (PMID 36345604, 2023). "The correlation between ITGAV and tumor immune cell infiltration, immune checkpoint, immune-related genes, ICB and drug response was also examined." (PMID 36388191, 2022). "Tumor cells with increased ITGAV expression show heightened cell migration in vitro and in vivo as well as an increased rate of cell proliferation." (PMID 35246597, 2022). "As an integrin receptor, ITGAV plays roles in a variety of biological functions that lead to tumor development." (PMID 36388191, 2022). "Using R package “ssGSEA” analysis, it was found thatthe ITGAV mRNA expression level showed intense correlation with tumor immunity, such as tumor-infiltrating immune cells and multiple immune-related genes." (PMID 36388191, 2022). "Limma was analyzed in high- and low-expression ITGAV samples to explore the potential mechanisms by which ITGAV promotes tumor progression." (PMID 36388191, 2022). "Tumor take rates were as follows: selectin k.o. mice injected with control cells: 8 of 13 (62%) and k.o. mice injected with ITGAV KD cells: 6 of 14 (43%)." (PMID 34174926, 2021). "The results of the IHC analysis showed that ITGAV was upregulated in ESCC tumour tissues compared to adjacent tissues." (PMID 34709754, 2021). "Results illustrated that ITGA2, ITGA3, ITGA4, ITGA6, ITGA11, and ITGAV transcripts were increased in ESCC tumour tissues (n = 95) compared with normal tissues (n = 11)." (PMID 34709754, 2021). "We next performed IHC staining using a tissue array, including tumour tissues (n = 105) and adjacent tissues (n = 72), to determine the protein levels of ITGAV." (PMID 34709754, 2021). "We next verified the protein levels of the integrin α‐subunits suggested to be differentially represented between samples at the mRNA level, including ITGA2, ITGA3, ITGA4, ITGA6, ITGA11, and ITGAV using 10 paired (tumour and adjacent) ESCC patient tissues." (PMID 34709754, 2021). "Specifically, PDX tumours characterized by increased ITGAV protein levels (case LEG74) were more sensitive to indomethacin than those with low ITGAV protein levels (case LEG92 and LEG84)." (PMID 34709754, 2021). "Combined depletion of ITGAV on the tumor cells and E- and P-selectins in the tumor-host synergistically almost abolishes intraperitoneal spread." (PMID 34174926, 2021). "The knockdown of ITGAV in PDA cells strongly reduces primary tumor growth, peritoneal carcinomatosis and spontaneous pulmonary metastasis." (PMID 34174926, 2021).
tumor (continued). "Here we present the first experimental study to investigate if ITGAV plays a functional role in PDA tumor growth and progression with a particular focus on intraperitoneal carcinomatosis." (PMID 34174926, 2021). "ITGAV was expressed in both tumor and stromal cells, and ITGAV expression was stronger in stromal cells compared to tumor cells." (PMID 33718208, 2021). "The results showed that ITGAV knockdown suppressed tumour growth in the shITGAV KYSE30 or shITGAV KYSE510 groups." (PMID 34709754, 2021). "In summary, biomarkers associated with both oncogenic (ITGAV, CEACAM1, CXCL1, IL-10RB) and tumor-suppressive actions (CEACAM1) were found to increase the diagnostic performance of HE4, CA125 and age in our study." (PMID 33075095, 2020). "Integrin alpha V (ITGAV), a transmembrane glycoprotein responsible for cell-to-matrix binding has been found to enhance tumor progression in several tumor entities." (PMID 33110104, 2020). "To analyze heterogeneity of ITGAV expression within the tumor we performed an analysis of 165 patients on our multi-spot TMA." (PMID 33110104, 2020). "In contrast its downregulation in circulating tumor cells (CTCs) suppresses tumor dissemination through modulation of the expression of ITGAV and ROCK1." (PMID 32013263, 2020). "c-Myc has been shown to be regulated by integrin alpha-V (ITGAV) through the activation of the FAK-p38-p90RSK signaling axis that promotes 3D tumor invasion." (PMID 31109134, 2019). "In the co-expression network data, IL-32 is correlated with integrin alpha V (ITGAV) functioning as a tumor promoter." (PMID 31263095, 2019). "Staining for COL6A1, ITGAV, and MB proteins indicated a preferential localization in the tumor stroma, with staining also identified in neoplastic cells." (PMID 30185791, 2018). "In contrast its downregulation in Circulating Tumor Cells (CTC), suppresses tumor dissemination through modulation of the expression of ITGAV and ROCK1." (PMID 28118616, 2017). "The rationale for targeting of ITGAV is their involvement in cell proliferation, migration, invasion, survival and angiogenesis, which are essential processes for primary tumor growth and metastasis formation." (PMID 25247809, 2014). "Collectively, these findings identify an EBV-regulated miR-10b-3p/ITGAV/STAT5-ERK1/2 axis in NPC and show that loss of miR-10b-3p promotes tumor growth and metastasis by relieving ITGAV repression, suggesting potential therapeutic targets for EBV-associated NPC." (PMID 42263107, 2026). "Finally, immunoassays showed a significant correlation between ITGAV expression and the infiltration level of various immune cells, further clarifying the critical role of ITGAV in the tumor immune microenvironment." (PMID 40018050, 2025). "This multi-dimensional approach provides a more comprehensive view of ITGAV’s functional roles in cancer, particularly in relation to the tumor immune microenvironment, and supports its reevaluation as a biomarker and potential therapeutic target in precision oncology." (PMID 40775249, 2025). "To investigate the expression of ITGAV in multiple digestive system cancers, we first examined the expression of ITGAV in tumor samples and normal samples using TCGA as well as GTEx databases, which showed that ITGAV expression was elevated in the majority of the tumors (18 of 34)." (PMID 40018050, 2025). "In our initial analysis of tumor samples and corresponding normal samples from multiple databases, we observed that ITGAV mRNA and protein expression were consistently elevated in various digestive system cancers represented by LIHC, PAAD, COAD, ESCA, and STAD." (PMID 40018050, 2025).
tumor (continued). "Through GO and KEGG analysis of the DEGs of ITGAV in digestive system cancers, we found that ITGAV was closely related to the organization processes of the extracellular matrix and was enriched in pathways regulating tumor cell migration and motility." (PMID 40018050, 2025). "Furthermore, we observed a consistent increase in ITGAV expression level that correlated with advancing tumor malignancy across various categories, including T-stage, N-stage, M-stage, and pathological stage." (PMID 40018050, 2025). "Knockdown of ITGAV inhibited the migration and invasion of tumor cells." (PMID 38374893, 2024). "Correspondingly, knockdown of ITGAV remarkably promoted tumor cell apoptosis." (PMID 38374893, 2024). "In the context of HCC, activated ITGAV has been shown to enhance tumour invasion and metastasis by promoting the transcription of genes involved in oxidative phosphorylation, a vital process in cellular metabolism responsible for ATP production via the electron transport chain." (PMID 39428564, 2024). "Genetic suppression of ITGAV was shown to impair the proliferation, survival and migration of cancer cells, suggesting that ITGAV could serve as a therapeutic target to inhibit tumor progression and metastasis." (PMID 38316881, 2024). "ITGAV, as a functional molecule, serves as a marker of tumor stem cells." (PMID 39239559, 2024). "Besides, the expression level of ITGB4 and ITGAV, integrin related to tumor metastasis, were also increased." (PMID 38724499, 2024). "We also demonstrate that activation of insulin-like growth factor-1 receptor (IGF1R) pathway in epithelial cancer cells is necessary to induce EMP and mesenchymal state acquisition in response to tumor microenvironment-derived factors, while promoting ITGAV expression." (PMID 39075581, 2024). "Spatial transcriptomics of samples of 3 patient cohorts with cRCC tumors indicates that COL4A1 and ITGAV are more autocorrelated in immunotherapy-exposed stroma compared to immunotherapy-naïve tumors, with high expression among fibroblasts, tumor cells, and endothelium." (PMID 39639369, 2024). "Moreover, ITGAV knockdown abrogated the migration and invasion abilities of tumor cells that were induced by NET-DNA." (PMID 38326837, 2024). "Additionally, ITGAV gene expression was significantly upregulated in HNSCC tumor versus adjacent normal tissues according to three GEO datasets (accession numbers GSE6631, GSE13601, and GSE30784)." (PMID 38534932, 2024). "Here, we performed a comprehensive bioinformatics analysis of multiple datasets derived from CRC patients and showed that elevated expression of NID1 and the genes ITGA3, ITGB1, and ITGAV, which encode NID1 receptors, is associated with poor prognosis and advanced tumor stage." (PMID 38001576, 2023). "Related studies have found that ITGAV signaling inhibits tumor cell apoptosis." (PMID 36388191, 2022). "In addition, based on a UMUC3 cell line-derived xenograft model, mice with ITGAV knock-down presented a markedly lower number of metastases and bone marrow infiltration than wild-type tumor-bearing mice." (PMID 36142576, 2022). "We also found that ITGAV expression was positively correlated with most immune checkpoint markers, and immune checkpoint genes were exactly an important factor leading to tumor immune escape, which further confirmed the important role of ITGAV in immunotherapy." (PMID 36388191, 2022). "This experiment mimicked the cancer‐associated extracellular microenvironment that involves fibronectin and integrin αvβ1 and suggested that ITGAV/B1 may be crucial to the fibronectin‐dependent retention of metastatic EVs in the tumour microenvironment." (PMID 35923105, 2022). "This explains the important role of ITGAV in tumor immunity." (PMID 36388191, 2022). "Therefore, this study provides insights into the potential role of ITGAV in tumor pathogenesis and demonstrates its application prospects as a potential biomarker for LGG." (PMID 36388191, 2022).